GJB2 (gap junction protein beta 2)
Diseases named in the same sentence as GJB2 in open-access papers (continued):
Sharing a sentence is not in itself a finding about the gene and the disease.
deafness (continued). "More drugs based on inhibition of inflammation in the inner ear could be tried to treat Gjb2-related deafness and cochlear sensory epithelial damage." (PMID 35688810, 2022). "Whether DEX has a direct therapeutic effect on hereditary deafness, especially GJB2-related deafness, remains unclear." (PMID 35688810, 2022). "Following Wilch’s publication hypothesized that some deafness could result from disruption of GJB2 cis-regulatory elements (CREs), we were the first to explore GJB2 cis-regulation." (PMID 34440441, 2021). "In the present study, we have also identified the missense/non-sense heterozygous variants in the OTOG p.(Val1813Gly), SLC26A4 p.(Tyr556∗) CDH23 p.(Ala1631Val), GJB2 p.(Arg165Trp), and MYO15A p.(Arg1965His) genes which are predominant to cause deafness among Indian populations." (PMID 34113375, 2021). "This patient presents mild deafness, which can be explained by GJB2 transcripts reduced by promoter variants, but not completely." (PMID 34440441, 2021). "This study aims to perform the functional assessment of pathogenicity of a rare recessive GJB2 variant c.516G>C (p.Trp172Cys) found in association with nonsyndromic deafness in indigenous peoples (Tuvinians and Altaians) of Southern Siberia (Russia)." (PMID 33466560, 2021). "Here, we analyzed clinical and molecular data from 21 Chinese deaf families who did not have hotspot mutations in the common deafness genes GJB2, SLC26A4, GJB3, and MT‐RNR1." (PMID 33095980, 2020). "However, when the mutation is in heterozygosis, as in most cases, it is necessary to do further analysis in the GJB2 gene, to investigate a possible compound heterozygosis as a justification of the manifestation of deafness." (PMID 30837189, 2020). "With regard to the responsible gene, the most frequent causative gene was GJB2 (29%), followed by SLC26A4 (9%), CDH23 (7%), MYO7A (4%), OTOF (5%), MYO15A (3%), and LOXHD1 (2%), indicating that these deafness genes are typical deafness genes found in the prelingual CI/EAS patients." (PMID 32027099, 2020). "Gene sequencing and analysis of deafness-related genes GJB2, GJB3, SLC26A4, and mtDNA did not reveal any mutation or SNPs in the patient and his mother." (PMID 31345197, 2019). "It was reported that GJB2 mutations are also associated with a large proportion of non‐syndromic deafness patients in Austria and Africa." (PMID 30693673, 2019). "In the current study, three known deafness genes (GJB2, TMPRSS3, and MYO15A) were detected in several pedigrees, suggesting that the strategy of proband-WES can be successfully applied to search for novel ARNSHL genes shared by multiple families with similar phenotype." (PMID 31379920, 2019). "In our study, gene sequencing and analysis of deafness-related genes GJB2, GJB3, SLC26A4, and mtDNA did not reveal any mutation or SNPs in the patient and his mother." (PMID 31345197, 2019). "We performed target region capture and next generation sequencing of 127 known deafness-related genes because the individual tested negative for hotspot variants in the GJB2, GJB3, SLC26A4, and MTRNR1 genes." (PMID 30068307, 2018). "Whether monoallelic GJB2 sequence alterations can be sufficient to determine deafness is currently unclear." (PMID 29320412, 2018). "However, nearly 10–50% of deaf subjects in many studies showing only one GJB2 mutant allele, further complicated the molecular diagnosis of DFNB1 deafness." (PMID 29921236, 2018). "Whether hearing loss in this group is due to unidentified additional variations within GJB2 or variations in other deafness genes is unknown in most cases." (PMID 28821934, 2017). "GJB2 deletion of Cx26 before, but not after, postnatal day 5 caused congenital deafness due to a closed cochlear tunnel." (PMID 28513246, 2017). "In this case study, we postulated that a combination of SLC26A4, GJB2 and SCARB2 heterozygous mutations may be implicated in deafness, whilst DUOX2 compound heterozygous mutations may be contributed towards thyroid dysfunction." (PMID 28222800, 2017).
deafness (continued). "Specifically, SH60-138 (grandmother of SH60-136) complained of perilingual deafness but did not carry p.R143W of GJB2, eliminating the contribution of this allele to prelingual profound SNHL if it segregated dominantly from SH60-138 to SH60-136." (PMID 27057829, 2016). "Thus, panel sequencing should be conducted to examine syndromic deafness genes as well as gap junction genes for definitive genetic diagnosis of GJB2 single heterozygotes in seemingly nonsyndromic SNHL in Koreans." (PMID 27057829, 2016). "Thus, through this analysis, the molecular etiology of deafness was confirmed in 23.56% (90/382) of the patients, and it involved the GJB2, SLC26A4, CDH23, MYO15A, and MT-RNR1 genes." (PMID 27018795, 2016). "Potential genetic causes for deafness in patients with the absence of GJB2 deleterious mutations remained unclear." (PMID 27082237, 2016). "Further, the authors propose that dominant GJB6 deafness mutations manifest themselves via their negative effects on heteromeric channels comprising normal Cx26 and mutated Cx30, and large deletions of GJB6 affect GJB2 expression." (PMID 25381570, 2015). "Bi-allelic GJB2 mutations were reported in 19.1% of patients with non-syndromic deafness, followed by bi-allelic SLC26A4 mutations in 12.1% and the mitochondrial MT-RNR1 mutations in 1.6%." (PMID 26011067, 2015). "Furthermore, because of the extreme heterogeneities of causative genes, studies of molecular etiology have focused mainly upon deafness genes, such as, GJB2, SLC26A4, or OTOF, which make larger contributions to deafness in local populations." (PMID 25373420, 2014). "Mutations in GJB2 are the most common cause of ARNSHL and explain up to 50% cases in the Mediterranean regions while mutations in multiple genes have been shown to cause deafness in the remaining cases." (PMID 24949729, 2014). "In Chinese Hans, for example, bi-allelic GJB2 mutations were reported in 19.1% of patients with non-syndromic deafness, followed by bi-allelic SLC26A4 mutations in 12.1% and the mitochondrial A1555G mutation of MT-RNR in 1.6%." (PMID 23767834, 2013). "Three prominent deafness-related genes, GJB2, SLC26A4 and mtDNA 12S rRNA, were analyzed." (PMID 24341454, 2013). "In addition to GJB2, SLC26A4 and MT-RNR1, a variety of less commonly screened deafness genes accounted for a significant portion of genetic causes of non-syndromic deafness." (PMID 23767834, 2013). "We further verified that the hearing loss could be accounted for by the p.V37I allele of GJB2, and not by other known deafness genes by targeted next generation sequencing (panel sequencing) of 82 known deafness genes (including GJB2, GJB3 and GJB6)." (PMID 23637863, 2013). "While screening with Sanger sequencing for GJB2 mutations is common, this is not the case for the other known deafness genes (> 60)." (PMID 22607986, 2012). "A chief role in deafness and skin pathologies is carried out by the GJB2 gene." (PMID 22547955, 2011). "A negative result for mutations in the GJB2 gene reduces the empirical risk of a genetic cause of deafness." (PMID 22183286, 2011). "GJB2 is responsible for up to 21% of cases of deafness in the Chinese population." (PMID 21122151, 2010). "Although loss of function mutations in Gjb2 impair cochlear development and are the most common cause of congenital deafness, it is not known if these variants disrupt spontaneous activity and the developmental trajectory of sound processing circuits in the brain." (PMID 37368868, 2023). "Assessment of the GJB2 and GJB6 gene expressions may improve our understanding of the function of different cellular networks in the human cochlea (HC) and how cell-specific changes and mutations may interact and cause Cx26/Cx30-based deafness." (PMID 36204137, 2022). "In addition, previous studies suggested that the sensitive period for successful CI outcomes for children with OTOF-related DFNB9 may be narrower than that for those with SLC26A4- and GJB2-related deafness." (PMID 32899707, 2020).
deafness (continued). "It was suspected that variants in few genes like STRC, GJB2, SLC26A4, OTOG or TECTA may explain the hearing loss for the majority of individuals in our cohort as is the case in many other world populations for the individuals with moderate to severe deafness." (PMID 32681043, 2020). "The most frequent causative deafness gene was TMC1 (DFNA36) (3 cases), followed by the next tier of genes (2 cases each) (CDH23, COCH, SLC26A4, TMPRSS3, ATP1A3), and the genes that were detected only once (ACTG1, GJB2, ILDR1, MYO7A, MYO15A, NF2, NLRP3 and SERPNB6)." (PMID 32238869, 2020). "Interestingly, there are great variations in the prevalence of patients with the GJB2 mutation in each population, suggesting that the allele frequency in the population, which reflects a founder effect, strongly affects the status of the GJB2 gene in the deafness population." (PMID 32120898, 2020). "About molecular analysis, individuals with deafness of unknown etiology and who lived in the Midwest state of Minas Gerais, Brazil, were investigated for the presence of 35delG and D13S1830 mutations in GJB2 and GJB6 respectively." (PMID 30837189, 2020). "A comparison of the positive diagnostic rate in the common deafness genes (GJB2, SLC26A4, and 12S rRNA) in this case cohort with that in a larger sample (16,456 cases) from our deafness genetic testing center revealed that our sample selection was representative of the Chinese deafness population." (PMID 31541171, 2020). "So the variation in 3’-UTR of GJB2 may also affect expression of GJB2 resulting to deafness." (PMID 30881389, 2019). "Another study used a comprehensive deafness gene panel (including 50 non-syndromic and 7 non-syndromic/syndromic deafness genes) to screen 125 deaf probands without common mutations in GJB2, SLC26A4, or MT-RNR1, and found potentially causative mutations in 26.4% (33/125) of the patients." (PMID 30682115, 2019). "It was observed in only one affected female partner of a DXN family in a heterozygous condition (E101Q/+) with no associated GJB2 mutations.There was no parental consanguinity in both the sides, but the wife’s side had history of deafness with four siblings affected." (PMID 29921236, 2018). "In the present study, definite genetic diagnoses could be achieved in 18 (9.6%) of the 188 families, comprising 13 (6.9%) with bi-allelic GJB2 mutations, three (1.6%) with bi-allelic SLC26A4 mutations, and two (1.1%) with homoplasmic m.1555A>G mutations, by screening the three common deafness genes." (PMID 30576380, 2018). "At the time of diagnosis, the absence of pathogenic variants in GJB2 gene had, in fact, misled the physician in reinforcing the hypothesis of an infective aetiology of deafness." (PMID 29142287, 2017). "In summary, we proposed that PDS in this family could be a polygenic disorder which possibly arises from a combination of heterozygous mutations in SLC26A4, GJB2 and SCARB2 which associated with deafness, as well as compound heterozygous DUOX2 mutations which associated with thyroid dysfunction." (PMID 28222800, 2017). "Based on the varying degrees of audiologic phenotypes of MITF-related WS2, including single side deafness, bilateral profound SNHL of SH107-225 may have resulted from the additive effect of single heterozygous c.235delC of GJB2, and the MITF mutation through digenic inheritance." (PMID 27057829, 2016). "The absence of mutation(s) in the GJB2 gene in other four subjects suggested the involvement of other modifier factors in the phenotypic manifestation of these putative deafness-associated 12S rRNA variants, as in the case of these families carrying the 1555A > G mutation." (PMID 21205314, 2011). "Of 44 subjects carrying one of definite or putative deafness-related 12S rRNA variants, only one subject carrying the 1413T > C variant harbored the 235DelC/299DelAT mutations in the GJB2 gene, while none of mutations in GJB2 gene was detected in other 43 subjects." (PMID 21205314, 2011).
deafness (continued). "The most interesting finding in our study was the absence of any mutation associated with deafness, including the commonly described mutations 35delG, 427C>T(R143W), 167delT, and 235delC in the connexin-26 (GJB2) gene in an ethnic group of the Iranian Arab NSARD patients." (PMID 20407643, 2009). "These mouse models have been instrumental in defining the physiological role of Cx26 in mammalian hearing and have served as in vivo platforms for testing emerging gene therapy and genome-editing strategies for GJB2-related deafness." (PMID 41516362, 2026). "Four recessive (TRIOBP, SLC26A4, GJB2, COL4A3) and one dominant (SOX10) for the deafness; six recessive genes (LRGUK, DNAH9, ARMC4, DNAH2, RSPH6A, and ACE) for male infertility can be conclusively ascribed." (PMID 38884051, 2024). "More importantly, hearing loss was detected in a Gjb2 R75W mouse model, but its endolymphatic potential was still within the normal range, which showed that impaired K+ circulation was not the main pathological mechanism of deafness caused by Gjb2 mutation but only a concomitant phenomenon." (PMID 37333892, 2023). "The most prevalent deafness genes identified in our cohort include SLC26A4 (22%), GJB2 (13%), MYO15A (6%), and OTOF (6%); whereas those identified in the American patients were GJB2 (36%), SLC26A4 (13%), MYO7A (8%), and MYO15A (8%)." (PMID 36009393, 2022). "In a study conducted in Iran, OR values were reported as 2.45 and 0.43 for GJB2 and GJB6 genes, respectively; accordingly, the possibility of deafness increased, compared to that reported for the control group." (PMID 33912482, 2021). "For hereditary deaf patients, extensive research has shown that the most common genes related to deafness include SLC26A4, mitochondrial 12SrRNA and GJB2." (PMID 31127414, 2019). "The discovery of the involvement of other deafness genes, including FOXI1 (MIM #601093), KCNJ10 (MIM # 602208) and GJB2 (MIM #121011) in combination with SLC26A4 monoallelic mutation has proposed the existence of digenic inheritance pattern in PDS and EVA." (PMID 28222800, 2017). "Overall, the clear contribution of GJB2, SLC26A4, and mitochondrial m.1555A > G to the etiology of the non-syndromic deafness population in south China was 32.0%." (PMID 24612839, 2014). "Therefore, association detection of GJB2, SLC26A4 and mitochondrial 12S rRNA was combined with hearing screening to determine the common sites and frequencies of newborn deafness gene mutation, which may be used to develop a more effective and earlier intervention for hearing disorders." (PMID 24348793, 2014). "TMPRSS3, MYO15A, GJB2, SLC26A4 were found to be responsible for deafness in autosomal recessive or sporadic families." (PMID 23967202, 2013). "TMPRSS3, MYO15A, GJB2, SLC26A4 were found to be responsible for deafness in autosomal recessive or sporadic families, while TECTA, WFS1, MYH9, EYA1, COL4A5 and COL11A1 were identified as the responsible genes for deafness in autosomal dominant families." (PMID 23967202, 2013). "The GJB2 and TECTA genes cause recessive non-syndromic deafness, and their variations have never been reported in TS-ANSD." (PMID 36837553, 2023). "The GJB2 (Gap Junction Beta 2) gene, which is located within the DFNB1 locus on 13q12 (hg19, chr13:20,500,000–21,525,000), accounts for the majority of NSHL and deafness." (PMID 35805969, 2022). "Some deletions impact only one other connexin gene, the GJB6 gene, but studies have described that DFNB1 deafness is not due to the GJB6 deletion but the dysregulation of GJB2 expression." (PMID 35805969, 2022). "Notably, large deletions in the GJB2 or GJB6 gene correspond with a monogenic or digenic mode of inheritance and induce deafness either in a homozygous or heterozygous state." (PMID 35457072, 2022). "In this study, we recruited 13 Chinese Han deafness families negative for GJB2, SLC26A4 and mitochondrial 12S rRNA." (PMID 36504663, 2022).
deafness (continued). "We recruited 13 Chinese Han deafness families who tested negative for GJB2, SLC26A4, and mitochondrial 12S rRNA." (PMID 36504663, 2022). "Furthermore, in Brazil, OR values of 11.7 and 0.46 were reported for GJB2 and GJB6 genes for the possibility of deafness, respectively, which increased in comparison to those of the control group." (PMID 33912482, 2021). "Here, we investigate the genetic etiology of deafness in two GJB2 and GJB6 negative patients presenting with pre-lingual, progressive, severe hearing loss." (PMID 33530996, 2021). "By controlling the concentration of SB in combination with CX26+ vesicle purification, large-scale production of highly purified iCX26GJCs for high-throughput screening of drugs that target GJB2-related deafness may be possible." (PMID 33968919, 2021). "Cx30 homozygous knockout-LacZ mice (Gjb6tm1Kwi/Gjb6tm1Kwi; MGI:2447863; EM:00323), hereafter abbreviated as Cx30−/−, are a model for humans in which large deletions in the DFNB1 locus lead to downregulation of both GJB2/CX26 and GJB6/CX30 and profound deafness." (PMID 33569381, 2020). "Due to limitations in mutation detection methodologies, most of the existing studies have focused on the three most common deafness genes, GJB2 (or Cx26), SLC26A4 (or PDS), and MT-RNR1, in the context of epidemiological studies or examining the correlation between CI outcomes and genotypes." (PMID 30682115, 2019). "Totally, 7 variants in 5 different genes were identified in 5 unrelated GJB2 negative families, suggesting the usefulness of this targeted massively parallel sequencing for comprehensive testing for all known deafness genes." (PMID 29568747, 2018). "The authors did not identify any GJB2 mutations, and reported the SLC26A4 c.919-2A>G mutation as the most common deafness mutation in the Mongolian patients." (PMID 30576380, 2018). "Biallelic GJB2 and SLC26A4 sequence variations with functional impact could be identified as the genetic determinant of deafness for two and one patient, respectively." (PMID 29320412, 2018). "The results of such an analysis are limited by the small number of people with a homozygous c.[35delG];[(35delG)] genotype, and there were only 2 children with heterozygous [GJB2:c.35delG];[GJB6:del(GJB6-D13S1830)] genotype giving the phenotypic effect of deafness." (PMID 27177978, 2017). "GJB2 and SLC26A4 are the two most common etiologies for deafness in the Chinese population." (PMID 19744334, 2009). "Taken together, these results suggested that GJB2 and GJB6 expression is interrelated at the transcription and translation levels in the cerebellum and cochlea, which may be regulated through the NF-κB pathway and contribute to deafness." (PMID 37178259, 2023). "Secondly, although the GJB2 and SLC26A4 genes are the major genetic causes of autosomal recessive non-syndromic deafness in the Chinese population, other related deafness genes that were not screened might have been missed." (PMID 38274112, 2023). "Snoeckx and colleagues proposed that Cx26G12V likely results in a defect in intracellular trafficking, like other non-truncating deafness mutants, but also emphasized that GJB2 deafness mutants, particularly the amino acid substitution mutants, reveal a wide range of often contradictory outcomes." (PMID 33807656, 2021). "However, compared with non-genetic deafness, such as GJB2- or SLC26A4-related deafness, shows greater tolerance to delayed implantation, as late as up to 35 months after CI, as evidenced by better speech performance." (PMID 34097718, 2021). "Connexin26 (Cx26, encoded by GJB2) mutations are the most common cause of non-syndromic deafness." (PMID 26927086, 2016). "No mutation was identified in GJB2 and in subsequent targeted NGS of 66 known deafness genes." (PMID 25759012, 2015).